HSPA8P4 (heat shock protein family A (Hsp70) member 8 pseudogene 4)
Gene: Processed pseudogene on chromosome 5 (130,140,031 to 130,141,950, forward strand). Ensembl gene ENSG00000248610.
Diseases named in the same sentence as HSPA8P4 in open-access papers:
HSPA8P4 is named in the same sentence as 1 disease in open-access papers, as found by Europe PMC text mining. Sharing a sentence is not in itself a finding about the gene and the disease. The quoted sentences say what the papers report.
tumor (2 papers, 2021 to 2022). "Univariate Cox regression analysis of clinical indicators revealed that T stage, N stage, M stage, pathologic stage, age, histological type, residual tumor, HSPA8P4, PHC1P1, RBMS1P1, LINC01303, and MSC-AS1 were meaningful, and the expression level of COL5A2 was also significant." (PMID 36447214, 2022).